RNU6-1208P (RNA, U6 small nuclear 1208, pseudogene)
Gene: Small nuclear RNA gene on chromosome 1 (24,777,873 to 24,777,979, reverse strand). Ensembl gene ENSG00000238482.
Homologues: Orthologues: chimpanzee U6 (99% identical), macaque U6 (89% identical), pig U6 (78% identical), guinea pig U6 (69% identical), guinea pig U6 (68% identical), guinea pig U6 (67% identical), guinea pig U6 (66% identical). Paralogues in human: RNU6-16P (81% identical), RNU6-1145P (80% identical), RNU6-1152P (80% identical), RNU6-1164P (80% identical), RNU6-15P (80% identical), RNU6-768P (80% identical), RNU6-80P (80% identical), RNU6-899P (80% identical), RNU6-959P (80% identical), RNU6-1011P (79% identical), RNU6-1013P (79% identical), RNU6-106P (79% identical), and 1283 more.